MYD88 (MYD88 innate immune signal transduction adaptor)
Diseases named in the same sentence as MYD88 in open-access papers (continued):
Sharing a sentence is not in itself a finding about the gene and the disease.
Hyperglycemia (12 papers, 2009 to 2025). An increased concentration of glucose in the blood. "Taken together, hyperglycemia caused by HFD intake can activate PKC-mediated TLR/MyD88/NF-κB signaling to secrete pro-inflammatory cytokines." (PMID 39947694, 2025). "Here, we hypothesize that MyD88, directly associated with hyperglycemia, could be directly involved in the cardiotoxicity and anticancer functions of ipilimumab." (PMID 33096896, 2020). "Hyperglycaemia has been shown to increase MyD88 independent and dependent signalling along with pro-inflammatory/angiogenic mediators downstream to MyD88 such as NFκB, VEGF, TNF-α and IL-1β." (PMID 38983565, 2022). "TLR4 signalling in RECs is attenuated by exchange protein activated by cAMP 1 (Epac1) leading to inhibition of hyperglycaemia induced MyD88-mediated signalling, suggesting that Epac1 acts upstream of TLR4 dependent signalling." (PMID 38983565, 2022). "Hyperglycemia/high‐concentration glucose (HG) activates Toll‐like receptors (TLRs)‐MyD88 in cardiomyocytes and heart tissues." (PMID 36180407, 2022). "In this study, we demonstrated that hyperglycemia reduces ipilimumab-related anticancer functions and enhances its cardiotoxicity in cellular models through mechanisms mediated by MyD88 and NLRP3 signaling." (PMID 33096896, 2020). "The second finding of this work is that Myd88−/− mice were more likely than WT controls to develop hyperglycemia upon β-cell insult." (PMID 19357791, 2009). "We found that Myd88−/− mice developed significant hyperglycemia relative to WT controls upon glucose challenge." (PMID 19357791, 2009). "Notably, shifting from hyperglycemia to hypoglycemia, as well as the treatment with empagliflozin, reduced the magnitude of these effects and expression of MyD88 both in MCF7, MDA-MB-231 cells, and AC16 cells." (PMID 33096896, 2020). "Both enhanced islet injury upon STZ treatment and diminished islet mass may contribute to the hyperglycemia seen here in Myd88−/− mice." (PMID 19357791, 2009). "We investigated SNP–SNP interactions between the TLR4 and MyD88 genes in CAD susceptibility and assessed whether the effects of such interactions were modified by confounding risk factors (hyperglycemia, hyperlipidemia and Helicobacter pylori (H. pylori) infection)." (PMID 26959040, 2016). "Thus, the novel interaction between TLR4 rs11536889 and MyD88 rs7744 was related with an increased risk of CAD, that could be strengthened by the presence of hyperglycemia or hyperlipidemia." (PMID 26959040, 2016). "A similar behavior was seen in cardiomyocytes: hyperglycemia increased expression of NLRP3 and MyD88 in a way that is sensitive to empagliflozin or shifting from high glucose to low glucose." (PMID 33096896, 2020). "In the current study, heterogeneity in the hyperglycemia or hyperlipidemia status of the study participants had a significant effect on the interaction of TLR4 rs11536889 and MyD88 rs7744." (PMID 26959040, 2016). "Our results suggest that miR-146a decreases the levels of hyperglycemia-induced TNFα possibly through the inhibition of HMGB1, TLR4, MyD88, and TRIF/IRF3 signaling." (PMID 26997759, 2016). "Therefore, we hypothesized that TLR4 and MyD88 were highly likely to be associated with hyperglycemia and hyperlipidemia, consistent with the effect-modification by hyperglycemia and hyperlipidemia that was observed in TLR4 rs11536889 and MyD88 rs7744 interaction." (PMID 26959040, 2016). "Under conditions of hyperglycemia, the OR (95% CI) was 4.905 (1.640–14.673) between TLR4 rs11536889 and MyD88 rs7744 (p value for interaction = 0.004)." (PMID 26959040, 2016). "In conditions of hyperglycemia, the interaction effect was strengthened between TLR4 rs11536889 and MyD88 rs7744 (p value for interaction = 0.004)." (PMID 26959040, 2016).
Hyperglycemia (continued). "It is interesting that neither genetic nor pharmacologic inhibition of MyD88 affected hyperglycemia in mice with T1D or T2D, indicating that the cardiac benefits observed in T1D and T2D mice were mainly due to the anti‐inflammatory effect of MyD88 inhibition." (PMID 36180407, 2022). "Interestingly, unlike ALOX5 and LTBR4, MYD88 expression was not modulated by hyperglycemia." (PMID 32273829, 2020).
hyperuricemia (12 papers, 2021 to 2025). An abnormally high level of uric acid. "In murine models, LLY-606 attenuates hyperuricemia-induced inflammation by inhibiting the TLR4/MyD88/NF-κB axis, reducing pro-inflammatory cytokine release and modulating the gut microbiota." (PMID 41141596, 2025). "The TLR4/MyD88/NF-κB and NLRP3 proteins are reported to be the major signalling pathways closely associated with renal inflammation caused by hyperuricemia." (PMID 36839325, 2023). "Increases hypoxanthine phosphate ribose transferase expression.Inhibits the uric acid synthesis by activating uric acid transporter.Inhibits NLRP3 inflammasome and TLR4/MyD88/NF-κB pathway.Regulates the composition and abundance of gut microbiota during hyperuricemia and renal inflammation." (PMID 36506033, 2022). "Probiotics and prebiotics were reported to reduce the levels of UA in hyperuricemia, regulating UA excretion and transportation, thereby inhibiting renal inflammation and inhibiting the TLR4/Myd88/NF-κB signaling pathway." (PMID 38674582, 2024). "Both EH-JAP and EH-LEU can alleviate hyperuricaemia and kidney inflammation in mice with diet-induced hyperuricaemia, possibly by inhibiting the TLR4/MyD88/NF-κB signalling pathway, thereby inhibiting uric acid biosynthesis and promoting its excretion." (PMID 37908979, 2023). "The molecular mechanism of its specific action may be related to the inhibition of the TLR4/MyD88 signaling pathway and the NLRP3 inflammasome activation, thereby reducing IL-1β production in high fructose-induced hyperuricaemia mice." (PMID 38041694, 2023). "Given that anserine decreased the expression of TLR4/MyD88/NF-κB and NLRP3 and elevated Nrf2 and TIMP1 in hyperuricemic rats, we speculate that anserine improves overall kidney function by decreasing inflammation, oxidative stress and cellular damage in hyperuricemia." (PMID 36839325, 2023).
osteoarthritis (12 papers, 2014 to 2025). A noninflammatory degenerative joint disease occurring chiefly in older persons, characterized by degeneration of the articular cartilage, hypertrophy of bone at the margins and changes in the synovial membrane. "Among the downregulated exosomal miRNAs derived from SERPINE1-silenced GC cells, miR-365a-5p has been reported to promote macrophage M2 polarization by inhibiting the TLR2/MyD88/NF-κB signaling pathway in osteoarthritis." (PMID 39748408, 2025). "In an in vitro LPS-induced osteoarthritis model, piperine treatment showed anti-inflammatory activity by downregulating miR-127 and MyD88 expression." (PMID 38731500, 2024). "Consequently, FTO overexpression suppressed synovial inflammation and alleviated osteoarthritis by inhibiting the miR-515-5p/TLR4/MyD88/NF-κB axis in an m6A-dependent manner." (PMID 39686999, 2024). "This study was conducted to identify whether the TLR4/MyD88/NF-κB signalling pathway plays a vital role in osteoarthritis (OA) treatment with Duhuo Jisheng Decoction (DHJSD) on the basis of a network pharmacology approach (NPA)-integrated experiment." (PMID 35140604, 2021). "Overexpressing FTO in osteoarthritis models improves cartilage integrity and diminishes inflammation by modulating TLR4/MyD88/NF-κB signaling and NLRP3 inflammasome activity, which are relevant in myocardial ischemia/reperfusion injury." (PMID 39980685, 2025).
renal fibrosis (12 papers, 2011 to 2025). A final common manifestation of a wide variety of chronic kidney diseases characterized by glomerulosclerosis and tubulointerstitial fibrosis. "Since few studies have focused on the direct association between MyD88 and TGF-β mediated renal fibrosis, further studies are needed to define the functional implications of MyD88 in the TGF-β/Smad signaling pathway." (PMID 34588982, 2021). "Previous studies demonstrated that the activation of the TLR/MyD88/NF-κB signaling pathway was intimately associated with the development of renal fibrosis, and that renal fibrosis and damage in the LN mouse model could be mitigated by inhibiting the TLR9/MyD88/NF-κB signaling pathway." (PMID 40593236, 2025). "The present study highlights the importance of the IL-1β/MyD88-induced inflammation signaling in the development of hepatic and renal fibrosis." (PMID 34764877, 2021). "Further studies demonstrated that TCSG from Baishouwu suppressed the development of hepatic and renal fibrosis through inhibiting MyD88 signal transduction activated by IL-1β and subsequent p38 MAPK and NF-κB p65 downstream signaling." (PMID 34764877, 2021). "The prevention of renal fibrosis through MyD88 inhibition results from the reduction of TGF-β1-induced EMT." (PMID 27246399, 2016). "In this study, we found that β-elemene attenuated renal interstitial fibrosis and down-regulated ECM protein expression in UUO mice by inhibiting STAT3 and Smad3 signaling via suppressing MyD88 expression, suggesting that β-elemene is effective in the treatment of renal fibrosis." (PMID 35628363, 2022). "Previous studies have shown that signaling factors such as JAK2/STAT3, Smad3, and Myd88 play a regulatory role in renal fibrosis, and β-elemene is a plant-derived sesquiterpenoid organic compound that has been shown to have anti-inflammatory, anti-cancer, and immunomodulatory effects." (PMID 35628363, 2022). "In addition, there are a series of Chinese herbal medicines to reduce renal fibrosis by inhibiting TLRs-MyD88 signaling-mediated inflammation." (PMID 35874522, 2022). "Moreover, because epithelial-mesenchymal transition (EMT) plays a role in renal interstitial fibrosis, we suggest that MyD88 inhibition attenuates renal fibrosis by blocking EMT." (PMID 27246399, 2016). "Therefore, MyD88 plays a critical role in EMT leading to renal fibrosis." (PMID 27246399, 2016). "Impaired TRIF rather than MyD88 signaling might account for less renal fibrosis in Tlr4-deficient mice." (PMID 21544241, 2011). "Meanwhile, we elucidated a novel cross-regulation between MyD88 and STAT3 or Smad3, thus reaffirming the plausibility of MyD88 as a potential therapeutic target for renal fibrosis." (PMID 35628363, 2022). "In conclusion, this experimental study shows that β-elemene reduces renal fibrosis by targeting JAK2/STAT3, Smad3, and Myd88 signaling factors and may serve as a potent inhibitor of STAT3 and Smad3 in the future." (PMID 35628363, 2022). "Furthermore, we clarified novel cross-regulation between MyD88 and the TGF-β/Smad pathway, thus identifying MyD88 as a potential therapeutic target in renal fibrosis." (PMID 34588982, 2021). "Although some studies have reported that MyD88 inhibition relieved renal fibrosis, the exact mechanism is not clear." (PMID 27246399, 2016). "In conclusion, our present study suggested that MA is not only a potential agent for reducing renal fibrosis by directly targeting TGF-β/Smad signaling, but also an effective inhibitor of MyD88 that may be involved in Smad4 nuclear expression or localization and NF-κB signaling." (PMID 34588982, 2021). "However, inactivation of this pathway in myeloid differentiation (Myd88) knockout mice consequently reduced renal fibrosis but not damage of tubules after AKI." (PMID 32059667, 2020). "These rather unexpected results are in accordance with the recent work of Anders's group showing that post obstructive renal fibrosis is independent of TLR2, TLR9 and MyD88." (PMID 24498450, 2014).
renal fibrosis (continued). "We therefore conclude that SIGIRR is redundant in UUO-induced renal fibrosis because TLR2-, TLR9- and MyD88 signaling do not significantly contribute to this model." (PMID 21544241, 2011).
type 2 diabetes (12 papers, 2010 to 2026). "Consequently, we measured circulating levels of insulin and leptin by ELISA, and found them to be elevated in MyD88-deficient mice, suggesting type 2 diabetes." (PMID 20824098, 2010). "The protein levels of the TLRs, TRAF-6, MyD88, and NF-κB were significantly increased in the adipose tissue of patients with type 2 diabetes." (PMID 28219358, 2017). "Finally, we show that targeting IEC MyD88 in diet-induced obese and type 2 diabetic animals strongly reduces fat mass, improves glucose metabolism and reduces inflammation." (PMID 25476696, 2014). "Cardiovascular outcome trials (CVOTs) suggest that GLP-1 RA could exert cardiorenal benefits and systemic anti-inflammatory effects in patients with type-2 diabetes through the activation of cAMP and PI3K/AkT pathways and the inhibition of NLRP-3 and MyD88." (PMID 39457081, 2024).
candidiasis (11 papers, 2010 to 2025). Infection with the organism Candida. "In this study we report the case of a 23-year-old woman with diffuse-type GC and recurrent candidiasis, in whom we identified a novel germline homozygous MYD88 variant." (PMID 26700889, 2016). "A role for TLRs in anti-fungal defense was first suggested by studies in mice deficient for the TLR adaptor MyD88, which are highly susceptible to systemic candidiasis." (PMID 25033445, 2014). "IL-1R1 also mediates the host response in pulmonary candidiasis, and we identified a similar role for IL-1R1 and MyD88 in trauma-induced and biofilm-associated Fusarium keratitis, indicating that the cornea employs similar responses to regulate infection by filamentous fungi." (PMID 20617171, 2010). "IL-1 cytokines have been suggested to protect from mucosal and invasive candidiasis mainly by recruitment and induction of anti-fungal effector mechanisms of neutrophils through cell-intrinsic and cell-extrinsic IL-1R/MyD88-signaling." (PMID 40097388, 2025). "Therefore, we next investigated these cytokines in the context of MyD88/IL-1β signaling and Treg functions during Candida infection in aged mice." (PMID 33240286, 2020). "In contrast, selective ablation of MyD88 in CD11c+ cells in CD11cΔMyD88 mice did not result in enhanced susceptibility to systemic Candida infection even though MyD88-deficient mice (lacking MyD88 in all cell types) were extremely susceptible." (PMID 25033445, 2014). "MiR-155 miRNA is down-regulated in individuals infected with invasive candidiasis, and cytokine is a target protein that is involved in inflammatory signaling including IRAK1, Traf6 and Myd88." (PMID 26313489, 2015). "Thus, ablation of Syk but not MyD88 in CD11c-expressing cells greatly compromises innate resistance to systemic C. albicans infection in mice and leads to death from fulminant candidiasis." (PMID 25033445, 2014).
cervical carcinoma (11 papers, 2012 to 2024). A carcinoma arising from either the exocervical squamous epithelium or the endocervical glandular epithelium. "The chronic inflammation mediated by TLR4/iNOS and TLR4/MYD88/NF-κB signaling pathway was associated with HPV-related cervical cancer." (PMID 36915050, 2023). "In contrast, LPS can bind to its receptor TLR4 and promote the proliferation of cervical cancer cells through the MyD88 and NF-κB pathways." (PMID 33456361, 2021). "The correlations between ICA and expression levels of TLR4/MyD88/NF-κB and Wnt /β-catenin signaling pathway were observed, for purpose of providing novel insight into cervical cancer." (PMID 33849528, 2021). "Our finding is consistent with predecessor's studies and confirmed that ICA suppressed the tumor progression of cervical cancer by inhibiting TLR4/MyD88/NF-κB and Wnt/β-catenin pathways in vitro and in vivo." (PMID 33849528, 2021). "In the present study, ICA has remarkably reduced the expression levels of TLR4, MyD88, NF-κB p65, Wnt 1, and β-catenin in cervical cancer SiHa cells." (PMID 33849528, 2021). "For the part of mechanism exploration, we showed that ICA inhibits the inflammation, proliferation, migration, and invasion, as well as promotes apoptosis and immunity in cervical cancer through impairment of TLR4/MyD88/NF-κB and Wnt/β-catenin pathways." (PMID 33849528, 2021). "Overall, we showed that icariin efficiently inhibits the inflammation, proliferation, invasion, as well as promotes apoptosis and immunity in cervical cancer by inhibiting TLR4/MyD88/NF-κB and Wnt/β-catenin pathways." (PMID 33849528, 2021). "Subtle but significant alterations in MyD88 mRNA expression were observed between chemosensitive and chemoresistant ovarian and cervical cancer cells." (PMID 24977712, 2014). "Furthermore, pro-inflammatory cytokines, such as COX-2, iNOS, IL-6, IL-8, MIP-3α, TGF-β1, and VEGF, are upregulated in HPV-related cervical cancer cells in vivo following the activation of the TLR4/MyD88/NF-KB pathway." (PMID 39451550, 2024). "Next, we sought to discover whether ICA inhibits cervical cancer progression through TLR4/MyD88/NF-κB and Wnt/β-catenin signaling pathways in vivo and in vitro." (PMID 33849528, 2021). "Interestingly, while MyD88 was downregulated in cervical cancer cell lines, SARM1 expression levels were upregulated." (PMID 29472602, 2018). "In line with our findings in diseased cervical stroma, TLR antagonists, for example, which act to block MyD-88, could confer therapeutic benefit in cervical cancer patients." (PMID 22013487, 2012). "Moreover, proinflammatory cytokines are highly expressed in HPV-related cervical cancer cells when the TLR4/MyD88/NF-κB pathway is activated, which indicates that TLR4 promotes cervical cancer progression via the formation of an immunosuppressive microenvironment." (PMID 32095158, 2020). "The same interaction was observed for human and mouse MyD88 and SPOP in human cervical carcinoma cells (Hela cells) and Chinese hamster ovary cells (CHO cells)." (PMID 32365080, 2020). "Two of the top ten pathways involved the myeloid differentiation factor 88 (MyD88), a protein involved in innate immune function that was upregulated in HPV-transformed cervical cancer cell lines." (PMID 32151264, 2020). "First, we observed that the adaptor molecule MyD88 was downregulated whereas SARM1 and TLR4 were upregulated in all three cervical cancer cell lines relative to normal keratinocytes." (PMID 29472602, 2018). "Western blot results showed that IgG did not affect the protein levels of MyD88, IRAK1, and TRAF6 (data not shown), indicating that TLR4 was at least the major target involved in IgG-mediated positive regulation of LPS-induced proinflammatory cytokine production in cervical cancer cells." (PMID 25179302, 2014).